MB (myoglobin)
Diseases named in the same sentence as MB in open-access papers (continued):
Sharing a sentence is not in itself a finding about the gene and the disease.
rhabdomyolysis (continued). "Clearance of circulating myoglobin is crucial to prevent further damage in patients with rhabdomyolysis (RM) and acute kidney injury (AKI)." (PMID 39927254, 2025). "Management of severe RYR-induced rhabdomyolysis presents significant therapeutic challenges, particularly in achieving effective myoglobin clearance and renal protection." (PMID 40909457, 2025). "Rhabdomyolysis is a clinical syndrome characterized by the breakdown of skeletal muscle tissue, leading to the release of myoglobin and creatine kinase (CK) into the bloodstream." (PMID 40843040, 2025). "The release and subsequent deposition of myoglobin in the kidneys result in acute renal failure (ARF) in up to 40% of cases of rhabdomyolysis and account for 7% of cases of ARF in the US." (PMID 40225506, 2025). "On admission, laboratory tests revealed markedly elevated CK (30,454 U/L), serum myoglobin (>3,000 μg/L) and creatinine (167 μmol/L), consistent with severe rhabdomyolysis and acute kidney injury." (PMID 40909457, 2025). "Hemoperfusion, used adjunctively in this case, is a promising yet investigational approach for enhancing myoglobin removal in severe rhabdomyolysis." (PMID 40909457, 2025). "Rhabdomyolysis is a clinical syndrome characterized by the breakdown of skeletal muscle tissue, leading to the release of intracellular contents such as myoglobin into the bloodstream, which can contribute to renal injury." (PMID 40305356, 2025). "Initial laboratory evaluation revealed markedly elevated creatine phosphokinase (CPK) and myoglobin, consistent with rhabdomyolysis." (PMID 40688837, 2025). "The pathophysiology of AKI in rhabdomyolysis includes intratubular obstruction by myoglobin casts, direct tubular cytotoxicity, and renal vasoconstriction." (PMID 41479675, 2025). "In rhabdomyolysis patients, myoglobin decreased from 18,976 (IQR: 1934–34,275) to 835 (IQR: 623–5925) μg/L (P=0.0273)." (PMID 41180104, 2025). "The current analysis examined the effects of hemoadsorption in patients with severe rhabdomyolysis (e.g. myoglobin > 10,000 μg/L) by comparing changes in myoglobin and creatinine levels over time and the associated clinical impact." (PMID 41398626, 2025). "Combined with the increase of LDH, α-hydroxybutyrate dehydrogenase, and myoglobin, and soy sauce-colored urine, the diagnosis of rhabdomyolysis in the patient is definite." (PMID 40587712, 2025). "The patients with septic shock exhibited significantly elevated IL-6 levels, while those with rhabdomyolysis demonstrated significantly elevated myoglobin levels." (PMID 41034327, 2025). "This case highlights the complexity and severity of drug-induced rhabdomyolysis with hemoadsorption playing a pivotal role in reducing myoglobin levels and improving the patient's condition." (PMID 39872682, 2025). "In the current analysis of the COSMOS registry, CS therapy rapidly improved myoglobin levels and kidney function in patients with severe rhabdomyolysis." (PMID 41398626, 2025). "At admission to ICU laboratory analyses confirmed severe rhabdomyolysis (CK 29,269 U/L, myoglobin 26,102 ng/mL), PCR diagnostics of tracheal secretions detected influenza B virus." (PMID 41267038, 2025). "Due to worsening hypoxemia, escalating norepinephrine requirements, and severe multiorgan dysfunction necessitating CRRT, along with aggravated rhabdomyolysis (myoglobin 41,000 ng/mL), the patient was deemed ineligible for ECMO rescue." (PMID 41561254, 2025). "The circuit incorporated a Jafron HA380 hemoadsorption cartridge (Jafron Biomedical Co., Ltd., Zhuhai City, China), aiming to enhance cytokine and myoglobin clearance in the context of fulminant septic shock and rhabdomyolysis." (PMID 41561254, 2025). "The patient had significantly elevated levels of myoglobin and creatine kinase, suggestive of rhabdomyolysis, likely resulting from the seizures, which are one of the characteristic manifestations of PRES." (PMID 40641529, 2025).
rhabdomyolysis (continued). "Patients were divided into those with persistent rhabdomyolysis (ongoing CK and myoglobin production from ongoing muscle injury) and those in which rhabdomyolysis was resolving." (PMID 39872682, 2025). "The vast majority of research on muscle injury indicators is limited to myoglobin and CK, and is based on rhabdomyolysis, exploring their effects on rhabdomyolysis and AKI." (PMID 40055771, 2025). "A 50‐year‐old woman with schizophrenia overdosed on risperidone, lormetazepam, and lorazepam and subsequently developed rhabdomyolysis, with elevated creatine kinase (CK) and myoglobin levels." (PMID 40635153, 2025). "Prospective studies are urgently needed to establish evidence-based protocols for optimizing myoglobin clearance and improving renal outcomes in severe rhabdomyolysis." (PMID 40909457, 2025). "In patients with rhabdomyolysis, median myoglobin levels significantly decreased from 18,976 (IQR: 1934–34,275) μg/L to 835 (IQR: 623–5925) μg/L (P=0.0273)." (PMID 41180104, 2025). "Several studies suggest that HCO dialysis is effective in reducing myoglobin levels in patients with rhabdomyolysis, particularly in cases of AKI." (PMID 39872682, 2025). "Rhabdomyolysis is a clinical syndrome characterized by the breakdown of muscle tissue, leading to the release of myoglobin into the bloodstream." (PMID 41398626, 2025). "The resulting condition is termed MH and leads to a plethora of pathological events, the most significant being rhabdomyolysis—a process in which the striated muscle cell ruptures, with a following efflux of intracellular enzymes, electrolytes, and myoglobin." (PMID 40429823, 2025). "In the current analysis, we analyzed CS use in patients with severe rhabdomyolysis, focusing on its impact on key laboratory and clinical parameters such as myoglobin levels, renal function, hemodynamic stability, and overall survival." (PMID 41398626, 2025). "Although myoglobin reaches its peak earlier than CK, both peaks are in the late stage of rhabdomyolysis and cannot be used as early predictive indicators of AKI." (PMID 40055771, 2025). "Recent research suggests that myoglobin, a heme-rich protein found in muscles, is one of the main factors for the creation and progress of rhabdomyolysis-induced AKI." (PMID 40271506, 2025). "The development of rhabdomyolysis is characterized by the release of large quantities of intracellular substances, including potassium, myoglobin, and creatine kinase (CK) into the circulation." (PMID 41246626, 2025). "It showed acute tubular injury with myoglobin, red cells, and granular casts, which were compatible with rhabdomyolysis-induced AKI." (PMID 39026342, 2024). "AKI is common in patients with rhabdomyolysis due to tubular blockage by myoglobin and intravascular hypovolemia due to fluid accumulation in the injured muscles." (PMID 39768744, 2024). "Further close laboratory checks revealed increasingly rising CK, CK-MB, and myoglobin values, as well as poorer kidney values (Cystatin C 0,98 – 1,12 mg/l) consistent with rhabdomyolysis." (PMID 39143959, 2024). "The pathophysiology of myoglobin has been widely studied in rhabdomyolysis, a condition consequent to muscle injury." (PMID 38036859, 2024). "In severe rhabdomyolysis, in which AKI develops in approximately 50% of cases, cases with a myoglobin/CK ratio exceeding 0.2 were reported to be at risk for AKI." (PMID 39347295, 2024). "CS is approved for use in rhabdomyolysis and its ability to eliminate myoglobin in patients with rhabdomyolysis has been previously demonstrated." (PMID 38907120, 2024). "Of the six rhabdomyolysis cases, five exhibited elevated serum levels of creatine phosphokinase, lactate dehydrogenase, and myoglobin, while levels were within normal limits in one case." (PMID 39130933, 2024). "This systematic, retrospective, single-center study analyzed 328 critical care patients with rhabdomyolysis (myoglobin > 1000 μg/l)." (PMID 38486159, 2024).
rhabdomyolysis (continued). "In case of severe muscle symptoms or coloured urine suspicious for rhabdomyolysis, they would advise to see the patient in the hospital, regardless of the results of the home measurement of urinary myoglobin levels." (PMID 38245779, 2024). "The role of myoglobin following primary injury and the subsequent cascade of events leading to rhabdomyolysis and AKI has been attributed to its effects on the proximal tubular epithelial cells." (PMID 39085790, 2024). "This case underscores the informative value of frequent monitoring of both CK and myoglobin to assess muscle damage severity and AKI risk in rhabdomyolysis, particularly with viral infections like COVID-19 that can cause delayed-onset muscle injury." (PMID 39347295, 2024). "The cytokine adsorber Cytosorb® (CS) can be used for extracorporeal myoglobin elimination in patients with rhabdomyolysis." (PMID 38907120, 2024). "In cases of rhabdomyolysis, efficient removal of myoglobin is crucial to protect the patient from acute kidney injury as well as for organ recovery." (PMID 39500494, 2024). "Two days later, the patient was found to have rhabdomyolysis, resulting in a renal biopsy that showed myoglobin cast nephropathy." (PMID 38375068, 2024). "Treatment of rhabdomyolysis is aimed at enhancing the clearance of myoglobin and managing AKI-related complications such as hyperkalemia and acidosis." (PMID 39026342, 2024). "Laboratory tests revealed significantly elevated levels of creatine kinase with N-acetyl cysteine (CKNAC) and the presence of myoglobin in the urine, confirming the diagnosis of rhabdomyolysis." (PMID 39105028, 2024). "Our case demonstrates the potential value of dual monitoring of myoglobin and CK in assessing muscle damage severity and AKI risk in persistent rhabdomyolysis." (PMID 39347295, 2024). "This revealed rhabdomyolysis with significantly elevated CK, CK-myoglobin (CK-MB) and myoglobin levels." (PMID 39143959, 2024). "Pigment-induced kidney injury commonly arises from the deposition of either myoglobin or hemoglobin, which are the end results of rhabdomyolysis and hemolysis, respectively." (PMID 39130933, 2024). "The patient with rhabdomyolysis presented with pain in the right calf and thigh, with initial laboratory findings showing myoglobin levels of 3010.3 ng/mL and creatinine kinase (CK) levels of 2630 IU/L." (PMID 39103536, 2024). "Even though the detection of myoglobin in the serum is considered pathognomonic for rhabdomyolysis, CK is considered a more useful marker for diagnosis and severity assessment, due to its delayed clearance." (PMID 39085790, 2024). "For this reasons, we defined rhabdomyolysis as myoglobin above 1000 μg/l in the range of published thresholds." (PMID 38486159, 2024). "One of the serious complications of rhabdomyolysis is acute kidney injury (AKI), caused primarily by myoglobin excreted through glomerular filtration, which induces tubule obstruction and oxidant injury." (PMID 39347295, 2024). "Abnormal urinary findings, such as the presence of blood and myoglobin were well-described in children with rhabdomyolysis and AKI." (PMID 39273741, 2024). "The early phase of rhabdomyolysis can be detected by measurement of the level of myoglobin, but the level normalizes rapidly once muscle injury ceases." (PMID 39347295, 2024). "Clearly less respondents measured myoglobin levels in serum (routinely: 19%, 7/37; in case of suspected illness/rhabdomyolysis: 46%, 17/37)." (PMID 38245779, 2024). "In conclusion, we advocate for a “paradigm shift” in managing severe rhabdomyolysis, recommending HA for CK levels >12,000 U/L and >10,000 ng/ml myoglobin, with column changes timed based on clinical condition and biomarker levels." (PMID 39223785, 2024). "Myoglobin and sarcoplasmic proteins are released from damaged muscles as a result of rhabdomyolysis, which is characterized by acute and severe muscular injury." (PMID 38629092, 2024).
rhabdomyolysis (continued). "19% (7/36) reported to advise urinary dipsticks to measure myoglobin levels to monitor rhabdomyolysis at home." (PMID 38245779, 2024). "The pathophysiology of rhabdomyolysis-induced AKI is mediated by a toxin known as myoglobin, which is present in vertebrate muscles with greater oxygen retention than hemoglobin and aids myocytes in obtaining energy." (PMID 36891010, 2023). "This case highlights the fact that typhoid-induced rhabdomyolysis is a serious, life-threatening disease and that the levels of CK and myoglobin are useful indicators for evaluating typhoid-induced rhabdomyolysis." (PMID 37972323, 2023). "In cases of severe muscle injury (rhabdomyolysis), much myoglobin (and consequently iron) can be released into the bloodstream." (PMID 38049866, 2023). "We show that therapeutic plasma exchange can be safely used for myoglobin clearance with critically ill patients with severe rhabdomyolysis." (PMID 37398832, 2023). "Myoglobin and inflammatory cytokines are believed to play a central role in the pathogenesis of rhabdomyolysis." (PMID 37398832, 2023). "The pathogenesis of kidney damage caused by snake envenomation includes direct venom cytotoxicity, systemic myotoxicity (rhabdomyolysis), accumulation of large amounts of myoglobin, and ischemia (brought on by systemic bleeding and vascular leakage)." (PMID 36833085, 2023). "In wasp sting clinical studies, elevated levels of myoglobin (in blood, urine, or both) and CK are typically used as biomarkers of rhabdomyolysis." (PMID 38376456, 2023). "Acute kidney injury (AKI) is one of the most severe complications after the occurrence of rhabdomyolysis and happens in 33-50% of patients with rhabdomyolysis because of the toxicity of myoglobin to kidney tubular cells." (PMID 36776867, 2023). "When there is an excessive release of myoglobin into the bloodstream, such as in cases of rhabdomyolysis, it can lead to the accumulation of myoglobin in the tubular cells of the kidneys." (PMID 37900084, 2023). "We reviewed 15 case reports and case series published between 2000-2021 that attempted myoglobin clearance in a total of 27 critically ill patients with rhabdomyolysis." (PMID 37398832, 2023). "Another possible mechanism involved in renal failure is rhabdomyolysis, with myoglobin release negatively impacting the outcome through intrarenal renal vasoconstriction, tubular ischemia, and tubular obstruction." (PMID 37685436, 2023). "Severe rhabdomyolysis frequently results in acute kidney injury (AKI) due to myoglobin accumulation with the need of kidney replacement therapy (KRT)." (PMID 37728069, 2023). "Upon hospital admission, blood tests including liver and kidney function tests, creatine kinase (CK) and myoglobin, along with blood gas analysis are recommended to detect for possible electrolyte, acid base disturbances and rhabdomyolysis." (PMID 38071341, 2023). "Myoglobin, a heme-containing protein, is nephrotoxic and responsible for the acute kidney injury often seen with rhabdomyolysis." (PMID 37344851, 2023). "PLA within wasp venom can attack the muscle cell membrane, damaging muscle cells and releasing myoglobin into circulation, leading to rhabdomyolysis." (PMID 38376456, 2023). "They propose the use of a Cytosorb® cytokine adsorber with simultaneous high-flux dialysis, highlighting the efficacy of myoglobin elimination in patients with rhabdomyolysis." (PMID 35897810, 2022). "In rhabdomyolysis-associated acute kidney injury (RM-AKI), the heme component of myoglobin can stimulate lipid peroxidation due to redox cycling of the heme group from ferrous to ferric and then to ferryl oxidation states, causing renal injury." (PMID 35294485, 2022). "His hospital course was complicated by acute kidney injury and, upon workup of his renal failure, was diagnosed with myoglobin cast nephropathy due to coronavirus disease 2019-mediated rhabdomyolysis." (PMID 36578087, 2022).
rhabdomyolysis (continued). "The pathophysiology of rhabdomyolysis-associated AKI is complex, but myoglobin related damage plays a major role." (PMID 35141180, 2022). "Myohemoglobin (myoglobin) is a harmful product of rhabdomyolysis, which is a clinical syndrome secondary to skeletal muscle injury." (PMID 35586503, 2022). "Myoglobin, creatine kinase, lactate dehydrogenase and creatinine are measured in our department only if there is clinical suspicion of rhabdomyolysis or kidney failure." (PMID 35862410, 2022). "Here we report the case of a 12-year-old boy with severe trauma-related rhabdomyolysis where we successfully utilized continuous renal replacement therapy in combination with Cytosorb® to eliminate myoglobin and prevent AKI." (PMID 35141180, 2022). "In this study, we established both cell and murine models of rhabdomyolysis‐induced AKI by using myoglobin and glycerin, respectively, and provided evidence that protein kinase Cδ (PKC‐δ) was activated in both models and subsequently promoted cell apoptosis." (PMID 35502493, 2022). "Rhabdomyolysis (RM) is a complex clinical syndrome characterized by damage to skeletal muscle cells and the release of cellular contents such as myoglobin (MB), creatine kinase (CK), and electrolytes into the blood circulation." (PMID 36259466, 2022). "The pathomechanism of rhabdomyolysis-induced AKI in the course of COVID-19 is based on the release of significant amounts of myoglobin, which results in myoglobinuria, and this leads to the formation of pigment casts." (PMID 35897810, 2022). "Standard treatment for rhabdomyolysis includes volume resuscitation and urine alkalization, aiming to improve kidney perfusion and excretion of myoglobin." (PMID 35340002, 2022). "As a good predictor of rhabdomyolysis-related acute kidney injury, an elevated serum myoglobin level was often observed after total aortic arch replacement combined with frozen elephant trunk implantation." (PMID 35273980, 2022). "We present this case to highlight a rarely reported finding of myoglobin cast nephropathy due to coronavirus disease 2019-mediated rhabdomyolysis." (PMID 36578087, 2022). "These substances, including myoglobin, creatine kinase (CK), potassium, and uridine acid, are markers of muscle damage and early complications of rhabdomyolysis." (PMID 35897810, 2022). "In this single-center retrospective study, we included patients with AKI and concomitant rhabdomyolysis (myoglobin >20,000 μg/L), who underwent at least one extracorporeal myoglobin removal procedure." (PMID 35340002, 2022). "Considering the mechanisms of rhabdomyolysis-associated AKI, the heme component of myoglobin can stimulate lipid peroxidation due to redox cycling of the heme group from ferrous to ferric and then to ferryl oxidation states, causing renal injury." (PMID 36293129, 2022). "Simultaneously, with the nephrotoxicity of myoglobin elucidated, the predictive value of serum myoglobin (sMb) for rhabdomyolysis-related AKI was reported in many surgical procedures." (PMID 35273980, 2022). "In our small retrospective study, we have shown a comparable effectiveness of a newer MCO membrane and a “standard” HCO membrane for myoglobin reduction in patients with rhabdomyolysis and severe AKI." (PMID 35340002, 2022). "Immediate injection of epinephrine, while maintaining renal function during the initial anaphylactic phase, would have prevented blood accumulation of myoglobin and uric acid due to rhabdomyolysis." (PMID 33970887, 2021). "The optimal cutoff for admission myoglobin to predict severe rhabdomyolysis defined by maximum myoglobin exceeding 5000 μg/L was 1938 μg/L, while it was 1193 μg/L to predict maximum CK exceeding 5000 U/L." (PMID 34559325, 2021). "On day 9, the patient had elevated creatine kinase and myoglobin levels consistent with rhabdomyolysis (26,046 U/L and 3668 ng/mL, respectively)." (PMID 33557936, 2021).